PPIH (peptidylprolyl isomerase H)
Description:
PPIase that catalyzes the cis-trans isomerization of proline imidic peptide bonds in oligopeptides and may therefore assist protein folding. Participates in pre-mRNA splicing. May play a role in the assembly of the U4/U5/U6 tri-snRNP complex, one of the building blocks of the spliceosome. May act as a chaperone.
Synonyms: CypH; USA-CYP; CYP-20; SnuCyp-20; MGC5016
Tractability: Small molecule: a structure with a bound ligand is known. PROTAC: ubiquitination databases record sites on it; its protein half-life has been measured.
Target class: Isomerase; Enzyme
Gene: Protein-coding gene on chromosome 1 (42,658,185 to 42,676,758, forward strand). Ensembl gene ENSG00000171960.
Subcellular location: Nucleus speckle; Cytoplasm
Pathways (Reactome):
Disease: SARS-CoV-1 activates/modulates innate immune responses
Metabolism of RNA: mRNA Splicing - Major Pathway
Gene Ontology:
Molecular function: peptidyl-prolyl cis-trans isomerase activity; protein binding; ribonucleoprotein complex binding; cyclosporin A binding
Biological process: positive regulation of viral genome replication; mRNA splicing, via spliceosome; protein folding; protein-containing complex assembly
Cellular component: cytoplasm; nuclear speck; U4/U6 snRNP; U4/U6 x U5 tri-snRNP complex; cytosol; nucleoplasm; spliceosomal complex
Genetic constraint (gnomAD): Loss-of-function variants: 13 observed, 26.36 expected, observed/expected ratio (o/e) 0.49, 90% interval 0.32 to 0.78. The upper end of that interval is the gene's LOEUF score, 0.78, which puts it in group 3 of 6, group 1 being the genes least tolerant of losing a copy. Missense variants: 148 observed, 217.33 expected, observed/expected ratio (o/e) 0.68, 90% interval 0.6 to 0.78. Synonymous variants: 60 observed, 76.92 expected, observed/expected ratio (o/e) 0.78, 90% interval 0.63 to 0.97.
Homologues: Orthologues: chimpanzee PPIH (100% identical), guinea pig PPIH (100% identical), macaque PPIH (100% identical), mouse Ppih (100% identical), pig PPIH (100% identical), rabbit PPIH (100% identical), tropical clawed frog ppih (92% identical), rat Ppih (87% identical), dog PPIH (83% identical), zebrafish ppih (78% identical), Drosophila melanogaster CG17266 (76% identical), Caenorhabditis elegans cyn-11 (68% identical). Paralogues in human: PPIE (56% identical), PPID (55% identical), PPIF (55% identical), PPIA (54% identical), PPIB (53% identical), PPIC (53% identical), NKTR (49% identical), PPIAL4C (49% identical), PPIAL4A (48% identical), PPIAL4D (48% identical), PPIAL4E (48% identical), PPIAL4F (48% identical), and 10 more.